NRG1 (neuregulin 1)
Diseases named in the same sentence as NRG1 in open-access papers (continued):
Sharing a sentence is not in itself a finding about the gene and the disease.
tumor (continued). "Some lineage differences in NRG1 expression were seen; squamous cancer types, such as SCCHN and ESCC, tend to have higher NRG1 expression, indicating a ligand-driven HER3 activation in these tumor types." (PMID 28899363, 2017). "In this study, we showed that DJ-1 knockdown results in significant reduction in cancer cell proliferation and migration in vitro and tumor growth in vivo, while DJ-1 overexpression elevates HER3 levels and promotes NRG-1-dependent HER3 signaling and tumor growth." (PMID 27582551, 2016). "While there appeared to be a trend toward elevated NRG1 levels and an increase in tumor shrinkage, neither elevated NRG1 nor reduced ERBB3 expression predicted for response to duligotuzumab or against response to cetuximab." (PMID 27843803, 2016). "To date, there is only one published clinical trial involving lapatinib (EGF104911) that measured NRG1 level in tumours by immunohistochemistry (IHC), but they did not mention any correlation between NRG1 and clinical benefits from lapatinib monotherapy." (PMID 25691057, 2015). "In postmenopausal women harbouring ER+ tumours, we also recorded a negative correlation between NRG1 and tumour E2 levels (r=-0.542, P=0.020)." (PMID 23991224, 2013). "HER3 is essential for HER2 driven tumourigenesis, and patients with NRG1 driven HER2 non-amplified tumours have been suggested to derive clinical benefit from HER2: HER3-directed therapies." (PMID 23991224, 2013). "Our results suggest that NRG-1 released from MC38CEA by ADAM17 activates ErbB2 phosphorylation, which could play a role in an autocrine tumor promoting network." (PMID 23251384, 2012). "Here,we observed a strong down-regulation of tumor suppressors such as p21 (a well-knowncyclin-dependant kinase inhibitor), p15 (that normally prevents the activation of the CDK byinhibition of the cyclin D complex) and NRG1, a major anti-proliferative gene." (PMID 23071568, 2012). "The other ligands, including Nrg-1, -2a, -2b, 3, and 4, were expressed at very low levels or their expression levels decreased during tumor progression (data not shown) and were not considered further." (PMID 20975924, 2010). "Interestingly, in line with our findings, it has been shown that transmembrane (class III) isoforms of NRG1 are more commonly over-represented than soluble (class I) forms in Schwann cell tumours, suggesting that differences between the isoforms may be relevant for tumour formation in vivo." (PMID 20668675, 2010). "The tumor promoting effect of the HCV transgene may be explained both by upregulation of pro-tumorigenic genes as Ubd, Erbb4, Nrg1, Ndrg1, Styk1, and by evasion of host defense response by viral proteins." (PMID 19340302, 2009). "Our study found that NRG1 levels were higher in CRPC patients compared to NCRPC patients, regardless of whether NRG1 was sourced from blood or tumor tissues." (PMID 40740239, 2025). "Notably, genes such as NRG1, SAMD13, MFAP3L, SALL1, ZNF704, SEMA5A, and HLA-DQB1 were identified as having altered expression patterns, potentially reflecting the diverse roles of FGFRS in tumor biology." (PMID 39676867, 2024). "Further, Zenocutuzumab (MCLA-128), a bispecific monoclonal antibody against ErbB2 and ErbB3, in the eNRGy study (NCT02912949) demonstrated durable efficacy and a well-tolerated safety profile in patients with advanced solid tumors harboring NRG1 fusion, regardless of tumor histology." (PMID 39123493, 2024). "Of note, p63 promotes mammary gland maturation via transactivation of NRG1 in the luminal layer by p63 in the basal layer, resulting in ERBB4/STAT5 signalling driving luminal differentiation, a process which remains to be validated in vivo in the tumour context." (PMID 38238426, 2024). "Therefore, we tested whether our BiXAbTM could block EGF/NRG1-induced AKT and ERK phosphorylation in six tumor cell lines." (PMID 37153618, 2023). "However, more IER3+ CAFs accumulated near NRG1+ malignant cells in tumor specimens from nonresponders." (PMID 37424047, 2023).
tumor (continued). "Thus, it is likely that the NRG1/HER3/YAP axis plays a role in regulating anchorage-independent growth and that this axis might contribute to tumor progression." (PMID 36765036, 2023). "Interestingly, PCI37A-AXLC2 cells did not express more NRG1 compared to vector control despite AXL being overexpressed, and cetuximab-resistant PDX tumor (UW-SCC25) did not express NRG1 even though they had AXL expression." (PMID 35461210, 2022). "First, gene fusions are considered strong oncogenic drivers and recent clinical data show strong efficacy of compounds targeting, e.g., neuregulin 1 (NRG1), neurotrophic tyrosine kinase receptor (NTRK) or anaplastic lymphoma kinase (ALK) fusions in patients across various tumor types." (PMID 36231142, 2022). "The current research identified that infiltrated dendritic cells in the tumor microenvironment could synthesize hormones and secret the paracrine factors such as TNF, WNT10A, PDGFA, and NRG1 which could sensitize sensory neurons to promote neuropathic pain associated with multiple cancers." (PMID 32434423, 2020). "HNSCC models expressing both NRG1 and high H11D levels demonstrated an anti-tumor response to treatment with KTN3379 in vitro, and this translated to significant single agent KTN3379 activity in cell line-derived and patient-derived HNSCC tumor xenografts in mice with the same biomarker profile." (PMID 28723928, 2017). "This confirms the previously reported CD74-NRG1 fusion and also suggests that the NRG1, NF1 and Hippo pathway fusions may play important roles in tumours without known driver mutations and that this prognostic factor may be associated with poor survival." (PMID 28637487, 2017). "The high prevalence of NRG1 expression in HNSCC, while necessary for full ErbB3 activation, may be insufficient to fully predict the anti-tumor activity of an ErbB3-blocking antibody and may explain why the clinical studies to date for anti-ErbB3 antibodies have not proven successful." (PMID 28723928, 2017). "KTN3379 exhibited significant anti-tumor only in models that expressed both NRG1 and high H11D levels (Cal27 and CTG-0434), but did not have significant activity in a NRG1 positive model with low H11D (CTG-0776) or vice versa, in a NRG1-negative model bearing high H11D levels (CTG-0840)." (PMID 28723928, 2017). "In addition to driving TNBC tumor formation, BRCA1-IRIS overexpression drives their intrinsic and acquired paclitaxel resistance, partly by activating autocrine signaling loops EGF/EGFR-ErbB2 and NRG1/ErbB2-ErbB3." (PMID 25583261, 2015). "Moreover, in ER+ tumours we observed significantly negative correlations between intratumour NRG1 and ESR1 levels in premenopausal (r=-0.604, P=0.017) as well as among postmenopausal women (r=-0.769, P=0.003, data not shown)." (PMID 23991224, 2013). "Interestingly, we also observed a trend of negative correlations between tumour NRG1 levels and estrogens in tissues and plasma where tumour NRG1 correlated negatively with E2 in normal tissue (r=-0.473, P=0.023)." (PMID 23991224, 2013). "Additionally, targeting heregulin or neuregulin 1 (NRG1), which activates the HER3 receptor, has been effective in combination with trastuzumab emtansine (T-DM1) and pertuzumab, inhibiting the NRG1/HER3 signaling pathway, leading to increased tumor suppression and extended tumor regression." (PMID 39001482, 2024). "Interestingly, KTN3379 did not result in anti-tumor activity in a NRG1-positive model (CTG-0776), suggesting that NRG1 positivity alone may not be sufficient to predict KTN3379 activity in HNSCC." (PMID 28723928, 2017). "However, as opposed to tumor cells, cardiac ErbB2 signaling is critically ligand (NRG-1)-dependent." (PMID 27596216, 2016). "We found that unlike NRG1, ErbB3 expression in HNSCC is highly prevalent but rarely overexpressed relative to other tumor types, as determined by mRNA analysis." (PMID 28723928, 2017).
tumor (continued). "We found that two NRG1 positive models (Cal27 and CTG-0434) exhibited an anti-tumor response to KTN3379 treatment, while a NRG1 negative model (CTG-0840) did not." (PMID 28723928, 2017). "Similarly, it also found that the mRNA expression level of NRG1 in the SCC group was independent of patients’ age (p>0.05), but significantly correlated with tumor pathological staging, surgical pathology staging and lymphatic metastasis (p<0.05)." (PMID 38952532, 2024).
cancer (186 papers, 2006 to 2026). A tumor composed of atypical neoplastic, often pleomorphic cells that invade other tissues. "In cancer, suppression of this axis is being tested with promising results in patients with tumors harboring NRG1 fusions or similar alterations causing aberrant activation or expression." (PMID 40469844, 2025). "NRG1 fusions represent important molecular events that are implicated in the tumorigenesis of various cancers." (PMID 40730881, 2025). "Functional studies discovered that overexpression of Lnc_025370 enhances the growth and metastatic capabilities of CHMp cells, which is associated with an increase in NRG1, and concurrently diminishes the anti-cancer effectiveness of C6 ceramide in vitro." (PMID 39727977, 2024). "NRG1 expression plays a pivotal role in the progression of cancer, especially in the context of KRAS mutations." (PMID 38957319, 2024). "NRG1 is also expressed in the heart, liver, kidneys, spinal cord, ovaries, and skin, and multiple fusions have been found in cancer; it has also been linked to cardiac development and disease." (PMID 38369520, 2024). "In pancreatic ductal adenocarcinoma (PDAC), cancer-associated fibroblasts (CAFs) secrete NRG1, which activates ERBB2 and ERBB3 receptor tyrosine kinases." (PMID 38957319, 2024). "NRG1-mediated autocrine signaling in cancer cells has been reported to underlie sensitivity to anti-HER2 therapies in certain ovarian and head and neck tumours." (PMID 33692466, 2021). "As expected, we also found that the cis-eQTL data showed that the variants in the NRG1 region were associated with the expression of NRG1 in both normal and cancer thyroid tissues from our RNA-sequencing results." (PMID 28703219, 2017). "We found several cellular growths or cancer-related pathways that were associated with SNPs of NRG1, VAV3, DIRC3, SEPT11 and INSR." (PMID 28703219, 2017). "Cancer-associated fibroblasts were found to secrete neuregulin-1 (NRG-1), which promoted proliferation via phosphorylation of ErbB3 and AKT in AsPC-1 PDAC cells." (PMID 21792199, 2011). "Cancer-associated fibroblasts-derived NRG-1 promote PDAC tumourigenesis via ErbB3-AKT signalling and overcomes single-agent EGFR inhibition." (PMID 21792199, 2011). "Screening for NRG1 fusions is like searching for a needle in a haystack, and diagnostic strategies can vary from one cancer type to another and from one medical center/healthcare system to another because of various workflow, technical, and medico-economic reasons." (PMID 40723230, 2025). "Whether it may offer greater value in defining patients at risk of cardiotoxicity from HER2-targetted cancer therapy and in identifying potential responders to recombinant NRG1 in clinical trials requires further research." (PMID 39180332, 2024). "In cancer patients, NRG1 fusion is linked to a poor prognosis." (PMID 36727079, 2022). "Interestingly, the neuregulin 1 secreted from cancer associated fibroblasts was recently shown to promote antiandrogen resistance." (PMID 35158801, 2022). "Collectively, this data suggest a HER3-independent role of NRG1 in cancer-associated fibroblasts that modulates their proliferation and migration and that could be driven by its intracellular domain (ICD)." (PMID 33692466, 2021). "NRG1 is silenced by methylation in some breast and other carcinomas and seems to be at least one target of distal 8p loss, which is one of the most frequent large-scale events in carcinomas." (PMID 33413557, 2021). "In conclusion, by showing that NRG1-dependent ErbB2–ErbB3 signalling is essential for the survival of differentiated trophoblast cell populations, we newly identify a physiological role for this cancer-associated receptor combination during human development." (PMID 26490994, 2015). "Here, we gather information on 665 reported patients with a total of 115 different known gene partners, and discuss structural elements supposed to play important roles in the biology of NRG1 fusions in cancer." (PMID 41992305, 2026).
cancer (continued). "We report the landscape of NRG1 fusion-positive cancers and highlight the importance of RNA testing." (PMID 41390931, 2026). "In the case of no access to RNAseq, NRG1 FISH consists of a valuable tool searching for NRG1 fusions in patients with advanced cancers." (PMID 40723230, 2025). "The CAF-derived factor NRG1 was demonstrated to modulate the therapeutic response in a variety of cancers." (PMID 40524253, 2025). "A total of 1,501 distinct fusions in at least one of the nine driver genes assessed (ALK, RET, ROS1, NTRK1/2/3, FGFR2, FGFR3, and NRG1) were detected in 1,497 patients for a combined prevalence of 2.2% across the pan-cancer cohort." (PMID 41091579, 2025). "In esophageal squamous cell carcinoma, NRG1 has been demonstrated to promote cancer cell proliferation, migration, and afatinib resistance." (PMID 41213930, 2025). "Addressing the dense stromal barrier, it reveals that the interaction between cancer cell NRG1 and CAF ERBB3 activates the STAT3 pathway, leading to the “ERBB3 inhibitor + stromal metalloproteinase activator” strategy." (PMID 41463034, 2025). "PDGFRα, the primary receptor for PDGFC, was inhibited using a PDGFRα inhibitor, which effectively suppressed the ability of cancer cell-CM to promote NRG1 expression in fibroblasts." (PMID 41213930, 2025). "qRT-PCR analysis showed that the mRNA expression levels of TIMP1, CDC25C, ATP2A1, and TIGD1 were upregulated in cancer cell lines compared to normal cell lines, whereas NRG1 and DMPK exhibited reduced expression in cancer cell lines." (PMID 41190067, 2025). "For example, a recent study showed that prostate CAFs secrete neuregulin-1 (NRG1) to promote anti-androgen therapy resistance through activation of HER3 cancer cell signaling." (PMID 40341770, 2025). "KRASG12C inhibitors, fibroblast growth factor receptor (FGFR) inhibitors, and neuregulin 1 (NRG1) fusion inhibitors show promise across multiple cancers, with ongoing trials evaluating their efficacy." (PMID 41179283, 2025). "NRG1 fusions can be found in diverse cancer types, albeit at a low rate — ~0.15–0.5% across cancers." (PMID 38369520, 2024). "A potential factor for resistance identified from our previous model analysis is the presence of high NRG1, while in patients it is an oncogenic feature observed across multiple cancer types." (PMID 38360930, 2024). "Initially, 29 cases of NRG1 translocations were identified by fluorescence in situ hybridization assay in multiple cancer types." (PMID 38173003, 2024). "Taken together, several drugs that target ERBB2/HER2 and/or ERBB3/HER3, including small molecule inhibitors and antibodies, have shown evidence of pan-cancer activity in NRG1 fusion bearing malignancies." (PMID 38369520, 2024). "Targeting ERBB2-ERBB3 signaling has emerged as a promising therapeutic approach for patients with NRG1 fusion-positive cancers." (PMID 38957319, 2024). "In conclusion, the strategy for screening NRG1 fusions in cancers is complex and requires further investigation." (PMID 38173003, 2024). "Seribantumab displayed anti-proliferative effects in several cancer models and its currently in clinical phase I and II against advanced solid tumours with NRG1 gene fusion." (PMID 39695132, 2024). "In the cancer realm, suppression of this axis is being tested and shows promising results in patients whose tumors harbor NRG1 fusions and similar alterations leading to aberrant activation/expression." (PMID 38369520, 2024). "This is in contrast to driver fusions in other cancers (e.g. EWS-FLI, NRG1, RET), which have often been clearly linked to cancer hallmarks such as activating proliferation, growth factor signaling or invasion/metastasis." (PMID 39149323, 2024). "While progression-free survival (PFS) was only 2.8 months, the authors advocated for afitinib in the treatment of cancers with NRG1 fusions." (PMID 39575425, 2024).